GSDME (gasdermin E)
Diseases named in the same sentence as GSDME in open-access papers (continued):
Sharing a sentence is not in itself a finding about the gene and the disease.
atherosclerosis (continued). "Importantly, this work opens new avenues for therapeutic strategies targeting GSDME-mediated mechanisms, with potential implications in the prevention and treatment of atherosclerosis." (PMID 37761020, 2023). "Interestingly, researchers have reported that GSDME expression is significantly elevated in macrophages within atherosclerotic lesions and contributes to the progression of atherosclerosis through pyroptosis, which can be significantly inhibited by the ablation of GSDME." (PMID 41550939, 2025). "However, the mechanism of GSDME involvement in atherosclerosis remains incompletely elucidated." (PMID 36807553, 2023). "Recent studies provide compelling evidence that autophagy plays a pivotal role in regulating gasdermin E (GSDME)-mediated pyroptosis, a form of programmed cell death that contributes significantly to inflammation and plaque instability in atherosclerosis." (PMID 40244103, 2025). "Under the context of atherosclerosis (AS), STAT3 binds to the GSDME promoter, potentiating GSDME transcription and subsequent enhancement of caspase-3 activity, as well as the cleavage of GSDME." (PMID 38584157, 2024). "Co-staining of GSDME and macrophage marker CD68 also showed that GSDME was localized in CD68-labeled macrophages, consistent with the results of human atherosclerosis single-cell analysis." (PMID 36807553, 2023). "In light of gasdermin E’s (GSDME) role in pyroptosis and inflammation, this study elucidates its function in atherosclerosis onset." (PMID 37761020, 2023). "GSDME-mediated pyroptosis has been shown to be induced by a variety of pro-inflammatory stimuli, including oxidized low-density lipoprotein (ox-LDL) in macrophages, which is a key contributor to atherosclerosis." (PMID 40244103, 2025). "This review highlights that GSDME-mediated pyroptosis contributes to the pathogenesis of atherosclerosis, myocardial infarction, nonischemic cardiomyopathies and hypertension-induced cardiac damage." (PMID 41550939, 2025). "Altogether, our data suggest that GSDME could be upregulated by ox-LDL to induce macrophage pyroptosis and promote the progression of atherosclerosis." (PMID 36807553, 2023). "Based on our findings that GSDME ablation suppresses atherosclerosis development in vivo and GSDME binds to caspase 3 to induce pyroptosis in ox-LDL-treated macrophages, we further hypothesized that GSDME ablation might attenuate macrophages’ inflammatory behaviors." (PMID 36807553, 2023).
nasopharyngeal carcinoma (11 papers, 2022 to 2025). A carcinoma arising from the nasopharyngeal epithelium. "Lobaplatin (chemical formula: C9H18N2O3Pt), a third-generation platinum anti-neoplastic drug, also causes GSDME-mediated pyroptosis in nasopharyngeal carcinoma by activating caspase-3 and regulating the proteasomal degradation of cIAP1/2." (PMID 35896522, 2022). "Radiation induced GSDME-mediated pyroptosis happens both in colorectal and nasopharyngeal carcinoma cells." (PMID 40256765, 2025). "We find that PJA1 facilitates docetaxel resistance by inhibiting GSDME-mediated pyroptosis in nasopharyngeal carcinoma cells." (PMID 38906860, 2024). "A recent study demonstrated that OTUD4 deubiquitinated and stabilized GSDME, thereby promoting GSDME-mediated pyroptosis and increasing radiosensitivity in nasopharyngeal carcinoma." (PMID 38104141, 2023). "Similarly, GSDME triggers irradiation-induced pyroptosis in nasopharyngeal carcinoma cells, and significantly reduced GSDME expression is observed in radioresistant nasopharyngeal carcinoma specimens." (PMID 40256765, 2025). "In nasopharyngeal cancer (NPC) cells, RT causes caspase-3-induced GSDME-dependent pyroptosis via the internal mitochondrial apoptosis pathway, moreover, the upregulation of GSDME was found to enhance pyroptosis and radiosensitivity of NPC cells in vitro." (PMID 38228635, 2024). "Consequently, targeting the OTUD4/GSDME pathway to trigger pyroptosis is a novel strategy to improve radiotherapy sensitization of nasopharyngeal carcinoma." (PMID 38104141, 2023). "Moreover, lobaplatin as a third-generation of platinum-based anti-neoplastic agent, induces GSDME-dependent pyroptosis in nasopharyngeal carcinoma (NPC) through caspase-3 activation and modulation of cellular Inhibitor of Apoptosis Protein 1/2 (cIAP1/2) proteasomal degradation." (PMID 41291696, 2025).
liver cancer (9 papers, 2020 to 2024). An epithelial or non-epithelial malignant neoplasm that arises from the liver. "Based on these results, researchers speculate that GSDME is an oncogene that is associated with the staging and poor prognosis of liver cancer." (PMID 39526199, 2024). "In HCC, studies that utilized samples from a TCGA database reported a lower overall survival rate for primary liver cancer patients in the high-expression group than that in the low-expression group, suggesting that GSDME is associated with a poor prognosis in HCC." (PMID 39526199, 2024). "Similarly, GSDME is overexpressed in liver cancer tissues, and its expression is positively associated with tumor stage and negatively associated with patient survival." (PMID 39526199, 2024). "Plicamycin treatment also decreases GSDME expression in a concentrate-dependent manner in both HeLa and human liver cancer cell line Huh7 cells, consistent with the Sp1 knockdown results." (PMID 38238307, 2024). "Immunohistochemical analysis of liver cancer tissues also showed a significant increase in GSDME protein levels in cancer tissues compared with normal tissues." (PMID 39526199, 2024). "Additional research will help to reveal the specific mechanism of double-edged-sword role of GSDME in liver cancer and provide new ideas and strategies for the treatment of liver cancer in the future." (PMID 39526199, 2024). "Activated caspase-3 cleaves the GSDME protein, thereby initiating the pyroptosis pathway and inducing pyroptosis in liver cancer cells." (PMID 39526199, 2024). "Arsenic trioxide nanoparticles (As2O3-NPs) also can trigger GSDME-mediated pyroptosis in liver cancer cells expressing GSDME." (PMID 39526199, 2024). "This indicates that GSDME has a potential cancer inhibitory effect and provides a new target for the treatment of liver cancer." (PMID 39526199, 2024). "When antitumor drugs act on liver cancer cells and successfully activate pyroptosis mediated by GSDME, these tumor cells receive a lethal insult, effectively promoting tumor cell death." (PMID 39526199, 2024). "Single-cell sequencing of the HCC tumor microenvironment has demonstrated that GSDME expression is significantly increased in liver cancer tissues." (PMID 39526199, 2024). "Further analysis indicated that lenvatinib upregulated the levels of GSDME in HCC cells and activated the N-terminal protein levels of GSDME, thereby inducing pyroptosis and promoting the death of liver cancer cells." (PMID 39526199, 2024). "Research on the role of GSDME in HCC progression may give rise to GSDME as a novel specific target for liver cancer detection, treatment, and prognosis, bringing new hope for HCC prevention and treatment." (PMID 39526199, 2024). "Because functional studies of GSDME in HCC are limited, the precise molecular mechanisms of GSDME in liver cancer remain unclear." (PMID 39526199, 2024). "GSDME is expressed in liver cancer cells and highly expressed in some immune cells." (PMID 39526199, 2024). "Thus, GSDME has a double-edged-sword role in liver cancer, with potential anticancer effects and promoting tumor progression." (PMID 39526199, 2024). "Studies have shown that GSDMC may act as an oncogene to promote the occurrence of colorectal and lung adenocarcinoma, while GSDME acts as a tumor suppressor in breast and liver cancer." (PMID 35008400, 2022). "Therefore, GSDME plays a crucial role in the drug treatment process for liver cancer." (PMID 39526199, 2024). "Recent studies have reported that, unlike those in most tumors, GSDME is highly expressed in liver cancer, and GSDME expression in HCC is negatively associated with prognosis, suggesting that GSDME may promote HCC." (PMID 39526199, 2024). "GSDME was also highly expressed in HepG2, HuH7, and MHCC97H liver cancer cells when using the same method." (PMID 39526199, 2024).
liver cancer (continued). "In this article, we have reviewed the role, related mechanisms, and clinical importance of GSDME at the onset and development of HCC to provide a theoretical foundation to improve the clinical diagnosis and treatment of liver cancer." (PMID 39526199, 2024). "Western blotting analysis of GSDME expression in five liver cancer cell lines (HepG2, HuH7, LM3, SMMC-7721, and BEL-7402) revealed that GSDME is broadly expressed in HCC." (PMID 39526199, 2024).
renal fibrosis (9 papers, 2021 to 2026). A final common manifestation of a wide variety of chronic kidney diseases characterized by glomerulosclerosis and tubulointerstitial fibrosis. "Upon ureteral obstruction, the activation of the TNF-α/caspase-3/GSDME pathway resulted in GSDME-mediated pyroptotic cell death, causing hydronephrosis and renal fibrosis, which ultimately promote the development of obstructive nephropathy." (PMID 35462927, 2022). "Regarding the pathogenic role of GSDME in UUO-induced renal fibrosis and inflammation, we further evaluated the role of GSDME in another CKD model." (PMID 34746148, 2021). "Additionally, studies have reported that pyroptosis in renal tubules, mediated by the TNFα/Casp3/GSDME signaling pathway, leads to tubular loss and renal fibrosis." (PMID 38785272, 2024). "In both 5/6 nephrectomy (5/6Nx) and UUO animal models accompanied by CKDs, GSDME knockout improves renal function and prevents the progression of renal fibrosis." (PMID 37500614, 2023). "In recent research, GSDME deficiency has been shown to attenuate AKI, and caspase-3/GSDME-induced pyroptosis leads to the occurrence and progression of renal fibrosis." (PMID 37500614, 2023). "These evidences suggest that GSDME-mediated pyroptosis promoted inflammation to modulate renal fibrosis and renal dysfunction in chronic kidney disease." (PMID 35462927, 2022). "Collectively, these results provide evidence that the activation of GSDME is critical in regulating both renal fibrosis and kidney dysfunction possibly via promoting inflammatory responses in CKD." (PMID 34746148, 2021). "To further validate the role of GSDME in renal fibrosis, we first overexpressed FL-GSDME in HK-2 cells." (PMID 34746148, 2021). "GSDME deletion alleviated renal fibrosis and inflammation in both unilateral ureteral ligation (UUO) and 5/6 nephrectomy (5/6Nx) models along with the attenuation of renal dysfunction." (PMID 34746148, 2021). "Our results demonstrated GSDME mediates the initiation of renal fibrosis and kidney dysfunction possibly via promoting inflammatory response." (PMID 34746148, 2021). "Researchers have detected the activation of Casp3 and the cleavage of the GSDME protein in a mouse UUO-induced renal fibrosis model, and knockout of GSDME or Casp3 inhibited tubular cell pyroptosis, thereby alleviating hydronephrosis, interstitial fibrosis, and inflammatory cell infiltration." (PMID 40563434, 2025). "Meanwhile, the overactivated METTL3/EVL m6A axis is a potential target for renal fibrosis therapy, which maybe be an important upstream of the regulation of GSDME." (PMID 38388468, 2024). "In contrast, GSDME overexpression had an adverse effect on renal fibrosis." (PMID 35462927, 2022). "However, additional evidence confirming the role of GSDME in regulating renal fibrosis and kidney function in different CKDs is required." (PMID 34746148, 2021). "In addition, administration of caspase-3 inhibitor Z-DEVD-FMK, which inhibits caspase-3-mediated GSDME cleavage, protected against renal fibrosis both in vivo and in vitro." (PMID 34746148, 2021). "The findings suggested that GSDME deletion could protect obstructed kidneys against renal fibrosis." (PMID 34746148, 2021). "In the present study, we also found that GSDME deletion exerted a renal protective effect in 5/6Nx CKD along with attenuated renal fibrosis, inflammation and renal dysfunction, which highlights that GSDME might contribute to the pathogenesis of different types of CKD via promoting inflammation." (PMID 34746148, 2021). "We demonstrated that TFNAs@PLT could reduce inflammation-mediated pyroptosis and apoptosis via Caspase-3/GSDME and NLRP3-mediated Caspase-1/IL-1β pathways in AKI, while also alleviating renal fibrosis through NLRP3/Caspase-1 and TNF-α/NF-κB pathways in CKD." (PMID 41355960, 2026).
renal fibrosis (continued). "We previously reported that Gasdermin E (GSDME)-mediated pyroptosis in renal parenchymal cells contributes to obstructive nephropathy, while deletion of GSDME in renal tubular cells fails to completely inhibit the development of renal fibrosis." (PMID 35941120, 2022).
Yersinia infection (9 papers, 2019 to 2025). "In particular, GSDME was shown to induce Caspase-8-driven pyroptosis in neutrophils, which helps to control systemic Yersinia infections." (PMID 37988464, 2023). "Additionally, caspase-3 and caspase-8-dependent pathways can induce pyroptosis: chemotherapeutic agents trigger pyroptosis via caspase-3-mediated cleavage of GSDME, while Yersinia infection induces pyroptosis through caspase-8-mediated cleavage of GSDMD." (PMID 40832104, 2025). "The view was expanded with the discovery of caspase-3-mediated gasdermin E (GSDME) cleavage in tumor cells induced by chemotherapeutic drugs, and caspase-8-related cleavage of GSDMD in mouse macrophages during Yersinia infection." (PMID 36209102, 2022). "Caspase‐3 can cleave gasdermins E (GSDME) and consequently trigger GSDME‐dependent pyroptosis downstream of LPS/TNF‐α/TAK1 inhibitor co‐stimulation or Yersinia infection or BRAF/MEK inhibitor co‐treatment." (PMID 34590363, 2021). "GSDME, which is activated by caspase-3 and mediates pyroptosis in other settings, does not contribute to cell death during Yersinia infection, indicating that other caspase-3/7 targets are likely responsible." (PMID 39058785, 2024). "Besides caspase-3–dependent pyroptosis, recent study indicated the apoptotic caspase-8 induces cleavage of GSDME and GSDMD to elicit pyroptosis during Yersinia infection, which implied that pyroptosis and apoptosis share many signal transduction pathways." (PMID 30804337, 2019). "Recent studies have indicated that apoptotic caspase-8 can also induce the cleavage of GSDMD and DFNA5/GSDME, thus inducing pyroptosis during Yersinia infection, which indicates that apoptosis and pyroptosis may share many signal pathways." (PMID 31501419, 2019). "In myeloid cells, acetyltransferase Yersinia outer protein J (YopJ) activated GSDME but not GSDMD by promoting RIPK1/caspase-8 pathway to induce myeloid cell pyroptosis and protect host from Yersinia infection." (PMID 38022612, 2023).
lymph node metastasis (8 papers, 2022 to 2023). "GSDME has also been found to be methylated in estrogen receptor‐positive breast cancer and associated with lymph node metastasis." (PMID 34553845, 2022). "There was a significant correlation between high expression of GSDME and postoperative survival status, lymph node metastasis, and caspase‐3 (p < .05)." (PMID 34553845, 2022). "The Cox univariate analysis showed that GSDME expression, caspase‐3 expression, TNM staging, lymph node metastasis, and tumor size were all meaningful variables that affected the survival time of patients after surgery." (PMID 34553845, 2022).
triple-negative breast carcinoma (8 papers, 2021 to 2026). An invasive breast carcinoma which is negative for expression of estrogen receptor (ER), progesterone receptor (PR), and human epidermal growth factor receptor 2 (HER2). "For instance, decitabine has been shown to upregulate GSDME expression, shifting apoptosis to pyroptosis in tumor cells, and pretreatment with decitabine has augmented the effectiveness of nanodrug-delivered cisplatin in triple-negative breast cancer." (PMID 38066523, 2023). "In triple-negative breast cancer models, TMAO induces caspase-3-mediated cleavage of Gasdermin E (GSDME) by activating the endoplasmic reticulum stress sensor PERK, leading to tumor cell pyroptosis." (PMID 41050671, 2025). "In triple-negative breast cancer (TNBC), GSDME is activated along with the overexpression of mitochondrial uncoupling protein 1 (UCP1)." (PMID 38066523, 2023). "GSDME is expressed at higher levels in EMT6 triple-negative breast cancer and at lower levels in 4TIE triple-negative breast cancer." (PMID 35896522, 2022). "It has been shown that in CM cells, clofarabine (Clo) induces GSDME-mediated apoptosis by activating T cell immunity through CCL5 and CXCL10, and FAK-mediated phosphorylation of GRB7 plays a key role in triple-negative breast cancer (TNBC) cell migration." (PMID 41216288, 2025). "Here, we show that tetraarsenic hexoxide induces the pyroptotic cell death through activation of mitochondrial reactive oxygen species (ROS)-mediated caspase-3/gasdermin E (GSDME) pathway, thereby suppressing tumor growth and metastasis of triple-negative breast cancer (TNBC) cells." (PMID 33558527, 2021).
lung adenocarcinoma (7 papers, 2022 to 2024). A carcinoma that arises from the lung and is characterized by the presence of malignant glandular epithelial cells. "Recent research has highlighted the significant role of gasdermin E (GSDME) in regulating and recruiting T cells in liver hepatocellular carcinoma and lung adenocarcinoma." (PMID 39544286, 2024). "In our study, we found that GSDME was highly expressed in lung adenocarcinoma cells." (PMID 37283803, 2023).
glioblastoma (6 papers, 2021 to 2025). The most malignant astrocytic tumor (WHO grade IV). "Of note, GSDME generally acts as a robust anti-tumor effector across cancers, except for liver and glioblastoma cancers." (PMID 41291696, 2025). "In glioblastoma, GSDME paradoxically promotes tumor progression: although cleavage occurs, active membrane repair mechanisms prevent effective pyroptosis, while GSDME still facilitates tumor cell invasion and suppresses T cell infiltration." (PMID 41291696, 2025). "GSDME knockdown in glioblastoma multiforme cells increased nuclear DNA damage and inhibited Galangin-induced pyroptosis." (PMID 38104141, 2023). "In another study on glioblastoma, researchers used genomic data to find that human gliomas express higher levels of GSDME than normal brains." (PMID 36091247, 2022). "Kaempferol has been shown to trigger GSDME-mediated U87 MG and U251 glioblastoma cell line pyroptosis by inducing high levels of ROS autophagy and activating inflammasome/caspase-1/IL-1β signaling in vitro and in vivo experiments." (PMID 36091247, 2022). "As a second-generation cyclin-dependent kinase (CDK) inhibitor, AT7519 suppresses human glioblastoma cell growth via the caspase-3/GSDME-mediated pyroptotic pathway, suggesting that AT7519 is a potential GBM treatment chemical agent." (PMID 38104141, 2023).
head and neck squamous cell carcinoma (6 papers, 2021 to 2025). A squamous cell carcinoma that arises from any of the following anatomic sites: lip and oral cavity, nasal cavity, paranasal sinuses, pharynx, larynx, and salivary glands. "Overexpression of GSDME was associated with poor survival of head and neck squamous cell carcinoma." (PMID 34925465, 2021). "Interestingly, a similar negative impact of GSDME on immune cell infiltration was observed in a study on head and neck squamous cell carcinoma, where the authors found that GSDME expression levels negatively correlated with CD8+ T cell and B cell infiltration." (PMID 40544161, 2025). "However, GSDME was also found to be overexpressed in head and neck squamous cell carcinoma, lung squamous cell carcinoma and cholangiocarcinoma." (PMID 34925465, 2021).